ZRANB3 (zinc finger RANBP2-type containing 3)
Description:
DNA annealing helicase and endonuclease required to maintain genome stability at stalled or collapsed replication forks by facilitating fork restart and limiting inappropriate recombination that could occur during template switching events. Recruited to the sites of stalled DNA replication by polyubiquitinated PCNA and acts as a structure-specific endonuclease that cleaves the replication fork D-loop intermediate, generating an accessible 3'-OH group in the template of the leading strand, which is amenable to extension by DNA polymerase. In addition to endonuclease activity, also catalyzes the fork regression via annealing helicase activity in order to prevent disintegration of the replication fork and the formation of double-strand breaks.
Synonyms: AH2; DKFZP434B1727; 4933425L19Rik
Tractability: PROTAC: ubiquitination databases record sites on it.
Gene: Protein-coding gene on chromosome 2 (135,136,916 to 135,531,228, reverse strand). Ensembl gene ENSG00000121988.
Subcellular location: Nucleus; Chromosome
Subcellular location (Human Protein Atlas): Nucleoplasm
Gene Ontology:
Molecular function: ATP hydrolysis activity; ATP-dependent DNA/DNA annealing activity; DNA endonuclease activity; DNA helicase activity; K63-linked polyubiquitin modification-dependent protein binding; protein binding; ATP binding; endonuclease activity; nucleic acid binding; zinc ion binding
Biological process: DNA damage response; DNA repair; replication fork processing; replication fork reversal; response to UV
Cellular component: chromosome; nuclear replication fork; nucleoplasm; nucleus
Genetic constraint (gnomAD): Loss-of-function variants: 101 observed, 108.86 expected, observed/expected ratio (o/e) 0.93, 90% interval 0.79 to 1.1. The upper end of that interval is the gene's LOEUF score, 1.1, which puts it in group 4 of 6, group 1 being the genes least tolerant of losing a copy. Missense variants: 1,129 observed, 1,193.4 expected, observed/expected ratio (o/e) 0.95, 90% interval 0.9 to 0.99. Synonymous variants: 363 observed, 416.04 expected, observed/expected ratio (o/e) 0.87, 90% interval 0.8 to 0.95.
Homologues: Orthologues: chimpanzee ZRANB3 (99% identical), macaque ZRANB3 (96% identical), pig ZRANB3 (85% identical), dog ZRANB3 (79% identical), rabbit ZRANB3 (78% identical), mouse Zranb3 (77% identical), rat Zranb3 (75% identical), tropical clawed frog zranb3 (61% identical), zebrafish zranb3 (54% identical). Paralogues in human: SMARCAL1 (21% identical), CHD7 (18% identical), CHD9 (17% identical), CHD6 (17% identical), CHD8 (16% identical), CHD2 (16% identical), CHD5 (16% identical), CHD4 (16% identical), CHD3 (16% identical), SMARCA2 (16% identical), CHD1 (16% identical), SMARCA4 (15% identical), and 18 more.
Diseases named in the same sentence as ZRANB3 in open-access papers:
ZRANB3 is named in the same sentence as 20 diseases in open-access papers, as found by Europe PMC text mining. Sharing a sentence is not in itself a finding about the gene and the disease. The quoted sentences say what the papers report.
type 2 diabetes (4 papers, 2019 to 2022). "For example, a recent genome-wide association study of 5231 African patients with type 2 diabetes identified a novel significant locus for type 2 diabetes called ZRANB3 (encoding zinc finger RANBP2-type containing 3)." (PMID 35138411, 2022).
endometrial carcinoma (3 papers, 2017 to 2026). A malignant tumor arising from the epithelium that lines the cavity of the uterine body. "Other evidence links endometrial carcinoma (EC) to ZRANB3 loss-of-function, as several EC mutants in the ZRANB3 ATP-ase core and HNH domain showed both compromised ATP-ase and nuclease activities." (PMID 41596226, 2026). "ZRANB3 variants have been found to be associated with several types of cancers such as endometrial carcinoma." (PMID 36268271, 2022).
Diabetes (2 papers, 2019 to 2025). "Genetic studies have identified African ancestry-linked variants, such as ZRANB3, that impair insulin secretion and increase diabetes risk, reinforcing the critical role of the insulin secretory pathway, where defects can directly contribute to the development of diabetes." (PMID 41030733, 2025).
Fanconi Anaemia (2 papers, 2018 to 2024). "Surprisingly, guides targeting the fork reversal factors (SMARCAL1, HLTF, ZRANB3, SHPRH) or components of the Fanconi Anaemia pathway were neither enriched nor depleted, despite previous studies suggesting a genetic interaction between some of these factors and PRIMPOL in transformed cell lines." (PMID 37971291, 2024).
breast carcinoma (1 paper, 2022). "Concerning our reported breast cancer-associated variant SNP, rs189581518 on ZRANB3 gene." (PMID 36268271, 2022).
gestational diabetes (1 paper, 2019). Carbohydrate intolerance first diagnosed during pregnancy. "It is noteworthy that there is a ClinVar record of a duplication in ZRANB3 associated with gestational diabetes (ClinVar Accession SCV000191187.1: see Web Resources)." (PMID 31324766, 2019).
leukaemia (1 paper, 2026). "Instead, it is noteworthy that NIH3T3 H-RasG12V-transformed fibroblasts, which promote uncontrolled leukaemia cell proliferation, were shown to be reliant on ZRANB3-supported DNA synthesis for their growth." (PMID 41596226, 2026).
lymphoma (1 paper, 2021). A malignant (clonal) proliferation of B- lymphocytes or T- lymphocytes which involves the lymph nodes, bone marrow and/or extranodal sites. "Loss of Zranb3 led to sharp increase in DNA damage and apoptosis in pre-tumoral B-cells, thus causing a significant delay in lymphoma development." (PMID 34201047, 2021). "Inhibition of Zranb3, alone or in combination with replication stress-inducing drugs, could provide a therapeutic benefit not only in MYC-driven lymphomas but also for other MYC-driven malignancies." (PMID 34201047, 2021).
mastitis (1 paper, 2023). Inflammation of breast tissue during lactation or postpartum due to an obstructed duct or infection. "In this study, the ZRANB3, PIAS1, ACTR3, LPCAT2, MGAT5, and SLC37A2 genes in Xinjiang brown cattle, which are associated with mastitis resistance, were identified using a GWAS." (PMID 37372369, 2023). "These six genes (ZRANB3, PIAS1, ACTR3, LPCAT2, MGAT5, and SLC37A2) are all potentially associated with mastitis resistance." (PMID 37372369, 2023).
Schimke immuno-osseous dysplasia (1 paper, 2021). A multisystem disorder characterized by spondyloepiphyseal dysplasia and disproportionate short stature, facial dysmorphism, T-cell immunodeficiency, and glomerulonephritis with nephrotic syndrome. "Mutations in SMARCAL1 lead to Schimke immuno-osseous dysplasia (SIOD), while HLTF/ZRANB3-deficient cells are vulnerable to replication stress and contribute to tumorigenesis." (PMID 34041245, 2021).
viral infection (1 paper, 2024). "However, recently, we reported that circumstances necessitating urgent DNA replication, such as acute responses to a mock viral infection (pI:pC injection), favored DNA fork repriming by PrimPol over fork reversal by Zranb3 or Smarcal1." (PMID 39044358, 2024). "However, neither Smarcal1 nor Zranb3 appear to be essential for the acute HSPC response to polyinosinic:polycytidylic acid (pI:pC) insult that mimics a viral infection." (PMID 39044358, 2024).
cancer (5 papers, 2017 to 2026). A tumor composed of atypical neoplastic, often pleomorphic cells that invade other tissues. "As for SMARCAL1, a possible ZRANB3 cancer-associated duality is intriguing, albeit at present it appears confined to this tissue." (PMID 41596226, 2026). "The majority of the tested cancer associated mutations yielded nucleolytically inactive ZRANB3 proteins." (PMID 28621305, 2017). "Strikingly, the identified cancer-related mutations included the missense mutations targeting both of the ZRANB3 catalytic active sites: the ATPase active site contained within the helicase core, and the endonuclease active site in the HNH domain." (PMID 28621305, 2017). "To investigate the functional significance of cancer associated ZRANB3 mutations, we purified relevant ZRANB3 mutant proteins and tested their enzymatic activities." (PMID 28621305, 2017). "At the protein level, ZRANB3 mutations occur at relatively low frequency compared to other alterations, as they are present only in some cancers and in less than 10% of patients overall and can correlate with moderate either up- or downregulation of ZRANB3 mRNA." (PMID 41596226, 2026). "Importantly, our findings allow us to interpret the functional significance of cancer associated ZRANB3 mutations." (PMID 28621305, 2017). "One of these comes from Myc-driven B-cell lymphomas, where inactivation of ZRANB3 impaired the capability of these cells to restore normal DNA replication by fork reversal and to suppress cancer development." (PMID 41596226, 2026). "Compared to normal tissues, ZRANB3 is more often upregulated than downregulated in cancer overall." (PMID 41596226, 2026). "This comprehensive review integrates the currently available yet fragmented literature on ZRANB3, both at the gene and protein levels, examines its regulation in cancer development, and discusses the evidence supporting its role as a tumour suppressor and prognostic biomarker." (PMID 41596226, 2026). "As a result, loss of RAD18 or UBC13 in BRCA1-deficient cancer cells does not abrogate reversed replication fork degradation, which is instead rescued upon knockdown of the fork reversal translocases SMARCAL1, ZRANB3 or HLTF." (PMID 38943334, 2024).
Tumor (3 papers, 2022 to 2026). "The same hypothesis might also be extended in this tumour to ZRANB3 in relation with WRN, as mutations in the helicase domain of the latter were suggested to be pro-oncogenic in a transgenic Eμ-Myc mouse model." (PMID 41596226, 2026). "Instead, the association of high ZRANB3 expression with worse prognosis in lung adenocarcinoma (LUAD) may reflect the deleterious effects of certain functional mutations as a strategy used by the tumour to sustain abnormal proliferation." (PMID 41596226, 2026). "Nevertheless, ZRANB3 can be also downregulated, an effect that can be more easily interpreted in light of its tumour-suppressor function." (PMID 41596226, 2026). "In the majority of tumours, ZRANB3 appears to be (i) abnormally expressed, either at high or low levels; (ii) mutated; or (iii) altered in copy number (copy number alterations, CNAs)." (PMID 41596226, 2026). "In tumour cells, ZRANB3 gene expression is deregulated, a condition that is frequently associated with poor survival and adverse clinical outcomes." (PMID 41596226, 2026). "Moreover, the opposite outcomes observed in different kidney cancer subtypes, which differ for their immune-infiltrative traits and specific biomarkers expression, suggest a tissue-specific tumour regulatory function for ZRANB3." (PMID 41596226, 2026).
ZRANB3 also shares sentences with these, for which no sentence is quoted: cervical carcinoma (1 paper); melanoma (1); myelogenous leukemia (1); peanut allergy (1); pulmonary hypertension (1); thrombotic microangiopathy (1); Type 1 diabetes (1).